NGB (neuroglobin)
Diseases named in the same sentence as NGB in open-access papers (continued):
Sharing a sentence is not in itself a finding about the gene and the disease.
cancer (continued). "Undoubtedly further studies are required to dissect the role of neuroglobin in tumorigenesis and sensitivity to chemotherapy, and to identify potential of interfering in neuroglobin-cytochrome c interaction in cancer cells for therapeutic purposes." (PMID 20640154, 2010). "Neuroglobin (NGB) is an oxygen-binding globin with overexpressed levels in some cancer cells." (PMID 38529189, 2024). "The possibility has been suggested that the oxygen available from neuroglobin may facilitate the survival of cancers in the brain; and, more generally, the evolution of neuroglobin—as of haemoglobin—emphasises that mammals are oxygen-dependent." (PMID 38020212, 2023). "NGB could be a promising strategy for cancer therapy by decreasing tumor metastasis through the suppression of GPR35/angiogenesis axis." (PMID 37005662, 2023). "Thus, it can be seen that the biological function of NGB is different in different cancer cells or tissues." (PMID 37005662, 2023). "Furthermore, ambiguous results have been reported in cancer cells, where NGB knockdown promoted cell growth or functioned as a tumor suppressor." (PMID 33924212, 2021). "Similarly, it was demonstrated that NGB displays a direct role in the adaptation of cancer cells to the increased oxidative stress by several mechanisms, including ROS scavenging and the potentiation of the antioxidant response." (PMID 33924212, 2021). "Neuroglobin (NGB) is an antiapoptotic protein upregulated by 17B-estradiol (E2) and is implicated in the ERα pathway (E2/estrogen receptor A), related to preserving cancer cell survival in stressor conditions." (PMID 33669559, 2021). "Thus, at least two different pools of NGB, cytosolic and mitochondrial, exist in the breast tissues and they can act to preserve cancer cell survival and resistance to environmental stresses." (PMID 34440755, 2021). "Remarkably, almost 20 years of scientific research have given a plethora of possible fascinating functions of NGB in both neurons and extra-nervous cancer cells that are defined not only by its whole cell concentration, but also by its intracellular compartmentalization." (PMID 32872414, 2020). "Here, the possibility that NGB levels could represent a pivotal regulator of integrated response of cancer cells to stress has been evaluated." (PMID 29216269, 2017). "Although a tumor suppressive function of transiently over-expressed NGB in hepatoma cancer cells has been described, other studies reported that NGB expression is differentially modulated by hypoxia and oxidative stress in cancer cell lines." (PMID 27149623, 2016). "Hypoxia is a common feature of solid tumors and the involvement of NGB in the short-term adaptation of cancer cells has been hypothesized." (PMID 27149623, 2016). "As a whole, these results suggest that NGB could act in cancer cells, like in neurons, as a compensatory protective protein activated in response to injuring stimuli and able to prevent mitochondria-dependent apoptosis." (PMID 27149623, 2016). "As a whole, present data might lead to a new direction in understanding NGB function in cancer opening new avenues for the therapeutic intervention." (PMID 27149623, 2016). "This suggests that NGB may be part of the defense mechanism established by cancer cells to counteract tumor environment stress condition by helping cells to survive." (PMID 27149623, 2016). "Although further studies are needed to better dissect the role of NGB in E2 cancerogenesis, the present data clarify the functional role played by NGB in tumor cells opening new avenues to develop therapeutic strategies against E2-related cancers." (PMID 25299774, 2014). "Present results indicate that the E2-induced NGB upregulation in cancer cells could represent a defense mechanism of E2-related cancers rendering them insensitive to oxidative stress." (PMID 25299774, 2014).
cancer (continued). "Moreover, NGB silencing in MCF-7 cells does not interfere with the E2-dependent increase of cell proliferation, highlighting that the NGB upregulation induced by E2 is specifically involved in protecting cancer cells against stress-induced apoptosis." (PMID 25299774, 2014). "In conclusion, the present results indicate that E2-induced NGB upregulation in cancer cells could represent a defense mechanism of E2-related cancers against oxidative stress." (PMID 25299774, 2014). "NGB, as a defense protein, could even render cancer cells insensitive to other stress inducers, such as chemotherapy and radiation." (PMID 25299774, 2014). "If neuroglobin-mediated protection from cell death is of physiological relevance, one could expect that cancer cells will also hijack this mechanism to advance their survival." (PMID 20640154, 2010). "Despite this, the levels of CYGB and NGB proteins were reported to generally be increased in different tumor sections in comparison to levels observed in corresponding normal tissues, leading the authors to suggest a contribution of both globins in promoting cancer survival under oxidative stress." (PMID 34440755, 2021). "Therefore, NGB may act in cancer cells as a functional hub that allows for the crosstalk between oxidative stress and inflammation pathways, which has recently been called “oxinflammation”." (PMID 33924212, 2021). "Since a bidirectional relationship between autophagy and mitochondrial metabolism was reported in cancer cells, in which mitochondria regulate the supply of free fatty acid by regulating the formation of autophagosomes, we investigated the effect of NGB overexpression on autophagy induction." (PMID 34943907, 2021). "As a whole, our results identified that NGB is released in the extracellular milieu under oxidative stress condition, and it can behave as an inter-cellular factor able to induce stress-adapted phenotype in cancer cells and promote mechanisms of tumor resistance to therapies." (PMID 32872414, 2020). "As a whole, such results open the fascinating possibility that, in cancer tissue, like in the brain, the NGB function in the cell adaptation response to oxidative stress might not be restricted to the intracellular environment but also spread to the extracellular microenvironemnt." (PMID 31354909, 2019). "Overall, beyond the contradictory evidence about the expression of NGB in tumor cells and tissues, mostly affected by experimental procedure, new perspectives regarding a possible role of the protein as a part of the defense mechanism against oxidative stress in cancer occurred." (PMID 31354909, 2019). "In this review, the involvement of NGB in the cancer cell adaptation and resistance to oxidative stress will be discussed highlighting the globin role in the regulation of both the stress-induced apoptotic pathway and antioxidant systems activated by cancer cells." (PMID 31354909, 2019). "Assessment of NGB expression by RT-PCR and Western blot in CRC cell lines and normal colon tissues showed that NGB was downregulated or silenced in cancer." (PMID 37005662, 2023). "In this study, we investigated the potential correlation between epigenetically regulation and function of NGB in CRC, in an attempt to explore the complex function of NGB in cancers." (PMID 37005662, 2023). "Finally, the involvement of AKT, SMAD2, SAPK/JNK, survivin, and protein stability, evidenced in this study, could converge in ROS-inducing pathways (e.g., Nuclear factor erythroid-derived 2, NRF2) to increase NGB levels and, ultimately, to cancer cell survival." (PMID 27149623, 2016). "Previously, we identified a novel pathway triggered by the sex hormone 17β-estradiol (E2) via the synergic action of both receptor subtypes (i.e., ERα and ERβ) that leads to the accumulation of neuroglobin (NGB) in the mitochondria of different cell types, including cancer and neuronal cells." (PMID 36982977, 2023).
cancer (continued). "On one hand, the enhanced expression of NGB in cancer cells and in the primary tumor of brain and non-brain origins (e.g., breast, lung) has been demonstrated and connected to the endogenous stress-related mechanism of cancer defense." (PMID 34440755, 2021). "Surprisingly, despite the dramatic decrease in circulating E2 in post-menopausal women, the levels of NGB did not change between pre-and post-menopausal cancer samples or in the activation of ERα or AKT." (PMID 34440755, 2021). "However, the molecular bases of NGB’s functions remain undefined, mainly in non-neuronal cancer cells." (PMID 33924212, 2021). "Overall, our hypothesis is that NGB plays a role in orchestrating stress adaptation in both neural and non-neural cells as well as in cancer." (PMID 34943907, 2021). "Indeed, on the one hand, NGB is a dynamic component of the cancer cell secretome that can affect the “response to stress” on neighbor cancer and non-transformed breast cells from the outside, eliciting their adaptation to microenvironmental stresses." (PMID 33924212, 2021). "Among different proteins that could serve as a compensatory element, here, we discuss the role of Neuroglobin (NGB), a monomeric heme-protein that operates as an oxidative stress biosensor and player in the context of the compensatory/adaptive systems of cancer cells." (PMID 31354909, 2019). "However, the involvement of NGB in cancer cell proliferation has not been confirmed by MCF-7 cell growth curves, which result similar to the control even when NGB was stably silenced." (PMID 27149623, 2016). "However, it remains unsolved the question about the possible role of endogenous NGB in non-nervous cancer cells as an oxidative stress sensor; this function requires NGB activation or induction by stressing conditions." (PMID 27149623, 2016). "Due to the low levels of expressed NGB, no NGB reactivity was reported in the cytosolic and mitochondrial fraction of normal tissues (data not shown), whereas a significant accumulation of NGB was reported not only in the cytosol, but also in the mitochondrial fraction of cancer tissues." (PMID 34440755, 2021). "Similarly, in other independent studies, the analysis of NGB in matched normal and cancer tissues has demonstrated the enhanced expression of NGB in primary tumors and cancer cell line of brain and nonbrain origins and its positive correlation with a marker of hypoxia conditions." (PMID 31354909, 2019). "Although the PathScan assay and NGB mRNA did not define a unique common pathway linking E2 and stressor-inducing NGB up-regulation, the results reported here clearly demonstrate that in MCF-7 cancer cells the apoptotic inducers modulate the level of NGB." (PMID 27149623, 2016). "Free RSV does not reduce NGB content in MCF-7 cancer cells when in concentrations lower than 1μM, nor could it have that effect on T47D cells, whose ERα expression is smaller than other E2-dependent cancer cells." (PMID 36768470, 2023).
tumor (11 papers, 2010 to 2023). "A good association between NGB accumulation and the grades of the tumor samples was highlighted." (PMID 34440755, 2021). "Analyses of the data set (e.g., GOBO) strengthen the idea that NGB accumulation could be linked to tumor cell aggressiveness (high grade) and resistance to treatment." (PMID 34440755, 2021). "Online database analysis and iTARQ assays were used to identify downstream targets of NGB related to tumor angiogenesis." (PMID 37005662, 2023). "Considering the inhibitory effect of NGB on tumor neovascularization in vitro and in vivo, we decided on investigating its underlying mechanism." (PMID 37005662, 2023). "Our data showed that the tumor-suppressive function of NGB was mediated by the inhibition of the GPR35/angiogenesis axis." (PMID 37005662, 2023). "In conclusion, we showed that NGB is epigenetically silenced and acts as a new tumor-suppressor gene in CRC." (PMID 37005662, 2023). "Flow cytometric analysis was performed to investigate the anti-tumor effects of NGB on cell cycle progression and apoptosis." (PMID 37005662, 2023). "To examine the effect of the NGB-mediated downregulation of GPR35 on tumor angiogenesis, we performed rescue experiments in HCT116 cells." (PMID 37005662, 2023). "NGB expression in eight paired clinical tissues was detected by qRT-PCR, and the results showed that NGB was lowly expressed in tumor 7 out of 8 pairs (87.5%)." (PMID 37005662, 2023). "GPR35, which scored high in the iTARQ assay, was negatively correlated with NGB and related to tumor angiogenesis." (PMID 37005662, 2023). "Tumor growth was markedly retarded, and tumor volume and weight were confined in the NGB-OE group (p < 0.05)." (PMID 37005662, 2023). "In this study, tube formation CCK8 and Transwell assays confirmed that NGB inhibited cell metastasis by suppressing tumor angiogenesis." (PMID 37005662, 2023). "Taken together, these results demonstrated that NGB suppresses tumor metastasis by downregulating GPR35 /angiogenesis axis probably." (PMID 37005662, 2023). "Western blot analysis showed that activation factors of the tumor angiogenesis pathway were downregulated following NGB-OE in HCT116 and Caco2 cells, including VEGFR2, p-VEGFR2 (Tyr1175), p-Src (Tyr416), p-AKT, and pErk1/2, but not AKT." (PMID 37005662, 2023). "NGB can be released in the tumor microenvironment by BC cells under oxidative stress conditions where it can act as an autocrine/paracrine factor to communicate cell resilience against oxidative stress and chemotherapeutic treatment." (PMID 35962042, 2022). "A significantly high NGB accumulation in G3 tumor tissue, which represents the most aggressive grade with marked variability, is reported." (PMID 34440755, 2021). "Although not statistically significant, this positive difference was found to be reverted in G3-grade patients: notably, OS is lower in a high-NGB-expressing tumor (red line) when compared to the low-NGB-expressing patients after three years (gray line)." (PMID 34440755, 2021). "Consistently with the high expression of NGB at a higher tumor grade, we observed an increase in NGB levels both in the mitochondrial and cytosolic compartments in G3 specimens if compared to G2." (PMID 34440755, 2021). "NGB is released in tumor microenvironment by BC cells only under oxidative stress conditions where it can act as autocrine/paracrine factor able to communicate cell resilience against oxidative stress and chemotherapeutic treatment." (PMID 32872414, 2020). "In fact, NGB co-localizes with the hypoxia-inducible metallo-enzyme carbonic anhydrase IX in different human primary tumor specimens." (PMID 27149623, 2016). "In addition, we noted that NGB inhibits metastasis in CRC not only tumor angiogenesis but also invasion/migration pathway, and we will make efforts to explore in future research work." (PMID 37005662, 2023). "The effect of NGB on tumor cell metastasis was assessed using Transwell assay." (PMID 37005662, 2023).
tumor (continued). "Data from TCGA online database combined with our experiments using clinical samples and CRC cell lines showed that NGB was epigenetically silenced in tumor tissues especially lower in liver metastasis tissues, suggested low NGB expression was correlated with metastasis in CRC." (PMID 37005662, 2023). "The results seem that GPR35 could be involved in the NGB-OE phenotype, NGB-suppressed tumor angiogenesis and cell metastasis by promoting GPR35 degradation." (PMID 37005662, 2023). "In addition, it had been reported that HCC cells overexpressed with NGB have a tumor-suppressive effect, in which NGB plays an important role in cell proliferation as the connection between O2/ROS signals and intracellular signals." (PMID 37005662, 2023). "Distinguished difference of promoter hypermethylation status between tumor and adjacent is identified in this study, implying that NGB could be considered as a predictive biomarker for early diagnoses for CRC." (PMID 37005662, 2023). "On other hand, a tumor suppression function for NGB accumulation has been proposed." (PMID 34440755, 2021). "Moreover, high-NGB-expressing tumor samples of G3 patients have a high significant (p = 0.001) lower 10-year RFS with respect to the low-expressing samples." (PMID 34440755, 2021). "Neuroglobin (NGB), a globin primarily described in neurons as an oxidative stress sensor and cytoprotective factor against redox imbalance, has been recently recognized as a novel tumor-associated protein." (PMID 31354909, 2019). "Here, the role of E2-induced NGB upregulation in tumor cells is reported." (PMID 25299774, 2014). "Previous studies identifying the potential anti-apoptotic role of neuroglobin raise the question as to how cells might employ neuroglobin to avoid the apoptotic impact of acute hypoxia whilst also avoiding chronic enhancement of tumour formation." (PMID 26305249, 2015). "The present study has allowed us to produce a mathematical model of the likely mechanism whereby human wild type neuroglobin can provide acute protection against hypoxia induced apoptosis, whilst avoiding chronic properties which might otherwise lead to enhanced tumour generation." (PMID 26305249, 2015). "Western blot and IF verified that VEGFR2 and tumor angiogenesis activation markers (p-VEGFR, pErk1/2, p-Src, p-AKT) were downregulated in CRC cell lines overexpressing NGB." (PMID 37005662, 2023). "Overexpression of NGB induced G2/M phase arrest and apoptosis, suppressed proliferation, migration, invasion in vitro, and inhibited CRC tumor growth and angiogenesis in vivo." (PMID 37005662, 2023). "The PCR results showed that ALB, ANGPTL7, IL6, and NGB were down-regulated in the BC tumor tissues, and BLOC1S5-TXNDC5 was up-regulated in the BC tumor tissues." (PMID 35962042, 2022). "The hypermethylation of NGB was detected in tumor tissue, but no or a very low methylation frequency in normal tissues." (PMID 37005662, 2023). "Tumor angiogenesis was activated in response to GPR35 restoration in the NGB absent group." (PMID 37005662, 2023). "In turn, as oxidative stress is a condition frequently occurring in tumor cells, we sought to determine whether E2-dependent NGB upregulation occurs in non-nervous cancers and is required for cell survival." (PMID 25299774, 2014). "Besides being a specific nervous system globin, contradictory evidences of NGB expression in non-nervous normal and tumor tissues have been reported." (PMID 25299774, 2014).